MDM2 (MDM2 proto-oncogene)
Diseases named in the same sentence as MDM2 in open-access papers (continued):
Sharing a sentence is not in itself a finding about the gene and the disease.
renal cell carcinoma (13 papers, 2011 to 2025). "The objective of the current study was to investigate the contribution of mouse double minute 2 (MDM2) genotypes and phenotypes to the risk of renal cell carcinoma (RCC)." (PMID 39857959, 2025). "For instance, MDM2 overexpression was associated with poor prognosis in renal cell carcinomas." (PMID 27659536, 2016). "The abnormal condition of VHL, HIF, MDM2, MDM4, and other genes linked to the development of renal cell carcinoma is closely related to the disappearance of its anticancer function." (PMID 37861516, 2023). "Overexpression of miR-215 reduced the expression of TYMS and MDM2 in renal cell carcinoma." (PMID 26317904, 2015). "To gather more evidence towards KLLN involvement in protein degradation, we used computational analysis of publicly available data from TCGA using the UALCAN web resource and observed that in renal cell carcinomas, KLLN, TRIM25 and MDM2 gene expression are positively correlated with each other." (PMID 33400740, 2020).
chondrosarcoma (12 papers, 2009 to 2026). A malignant cartilaginous matrix-producing mesenchymal neoplasm arising from the bone and soft tissue. "The significant immunoexpression of IMP3, CDK4 and MDM2 in metastatic Chondrosarcoma and the lower survival in those with positivity for MDM2, suggest a possible association of these proteins with tumor aggressiveness." (PMID 39368400, 2024). "The positivity of IMP3, CDK4, MDM2 and β-catenin antibodies was directly proportional to the increase of histological grade in Chondrosarcoma." (PMID 39368400, 2024). "Archival material from three extraskeletal myxoid chondrosarcomas, five chordomas, five chondromyxoid fibromas, five chondroblastomas and 25 chondrosarcomas was stained with antibodies against osteonectin, bcl-2, cox-2, actin, calponin, D2-40 (podoplanin), mdm-2, CD117 (c-kit) and YKL-40." (PMID 19594492, 2009). "In contrast to all other tumors, two of three extraskeletal myxoid chondrosarcomas were also positive for CD17 and negative for osteonectin, cox-2, mdm-2 and actin." (PMID 19594492, 2009).
cutaneous melanoma (12 papers, 2018 to 2025). A primary melanoma arising from atypical melanocytes in the skin. "This study highlights the importance of considering SURVIVIN and MDM2 expression in patients undergoing ILP for in-transit cutaneous melanoma metastases." (PMID 38138884, 2023). "MDM2 is a well-established oncogene in human cutaneous melanoma and functions to antagonize the activity of TP5346." (PMID 30664638, 2019). "The aim of the study was to evaluate the correlation between treatment response and clinical outcome of patients treated with ILP for in-transit cutaneous melanoma metastases and cancer levels of SURVIVIN and MDM2." (PMID 38138884, 2023).
dedifferentiated liposarcoma (12 papers, 2017 to 2025). A high-grade subtype of liposarcoma (LS) that progresses from well-differentiated liposarcoma (WDLS), and most often occurs in the retroperitoneum. "Dedifferentiated liposarcoma (DDLPS) also often has amplifications of the MDM2 and CDK4 genes." (PMID 41123840, 2025). "Dedifferentiated liposarcoma (DDLPS) is a highly morbid mesenchymal tumor characterized and driven by genomic amplification of the MDM2 gene." (PMID 31620242, 2019).
diffuse large B-cell lymphoma (12 papers, 2008 to 2024). "The genes BCL2 and MDM2 are also upregulated in lymphoid neoplasm diffuse large B-cell lymphoma." (PMID 34422220, 2021). "The first group included patients [three patients with diffuse large B-cell lymphoma (DLBCL) and one patient with Burkitt lymphoma] who exhibited gain of chromosome 12, which is where STAT6, MDM2, and BCL7A are located." (PMID 34710202, 2021).
head and neck cancer (12 papers, 2008 to 2024). A primary or metastatic malignant neoplasm affecting the head and neck. "Several additional associations correspond to dependencies on upstream regulators of cancer genes such as MDM2 in skin and kidney cancers and EGFR in head and neck cancer." (PMID 35382456, 2022).
brain tumors (11 papers, 2009 to 2025). "Four of these trials include brain tumor patients, but only two active studies are specifically focusing on MDM2 inhibitors for GBM." (PMID 37509518, 2023). "Collectively, the results of this study support the further development of SP-141 and/or its derivatives as innovative MDM2-targeted therapeutic strategies for combating brain tumors." (PMID 32630235, 2020). "The Dana–Farber Cancer Institute is sponsoring a clinical study to investigate the MDM2 inhibitor ALRN-6924 as a monotherapy for different types of cancer, including leukemia, brain tumors, solid tumors, and lymphoma." (PMID 37509518, 2023). "Notably, important oncogenes involved in brain tumor development are located on these chromosomes, such as PDGFR1 and FGFR2 on chromosome 4, EGFR and MET on chromosome 7, and CDK4 and MDM2 on chromosome 12." (PMID 41323387, 2025).
metastatic disease (11 papers, 2014 to 2025). "The amplification of CDK4 (p = 0.090) and MDM2 (p = 0.067) was found to be associated with an increased risk of metastatic disease." (PMID 36464833, 2023). "We found that 40% (14 cases) of GIST has shown immunohistochemical overexpression of MDM2, with 11/14 cases harboring high risk tumors and 8/14 cases presented with metastatic tumors." (PMID 29410603, 2018). "Higher median H-Scores of MDM2 were detected in tumors compared to normal tissue and metastatic tumors, whereas the highest values of MDM2 expression (H-Score: 300) were detected only in tumor tissues." (PMID 41514585, 2025). "MDM2 overexpression was a prognostic of the development of metastatic disease as well as overall mortality." (PMID 35548335, 2022). "The results revealed that the control group exhibited higher expression levels of p-AKT, p-MDM2, and E2F1 in lung metastatic tumors compared to the NCAPD2 knockdown groups." (PMID 41319185, 2025). "However, one was proved to be a metastatic tumor, and another was revised as DDL (case 32) which was MDM2-amplified but DDIT3-nonrearranged." (PMID 36059611, 2022). "Thus, targeting MDM2 and MDMX in TNBCs may have more benefit for diagnosis through liquid biopsy and for targeting metastatic disease, rather than in treating patients’ primary tumors." (PMID 30642351, 2019).
renal carcinoma (11 papers, 2015 to 2022). A carcinoma arising from the epithelium of the renal parenchyma or the renal pelvis. "This analysis indicated that MDM2 was consistently expressed at a high level in the surgical specimens of renal cancer, thymic tumor, and GIST." (PMID 28258440, 2017). "For example, MDM2, SLC16A3, LFT etc. show expression change in renal cancer; SLC22A7, ACHE, BMP4 etc. are associated with renal function." (PMID 27258182, 2016). "NME2 was also found to interact with MDM2 (Mouse double minute 2 homolog) to reduce the motility of renal carcinoma cells." (PMID 25700270, 2015). "We also confirmed that S9 could bind mouse MDM2 in Renca cells which is a murine renal carcinoma cell line by CETSA assay." (PMID 36071402, 2022). "Different strategies have been adopted in this direction, including the use of the MDM2 antagonists; however, no relevant drug has been able to to achieve satisfactory effects in renal cancer." (PMID 30874541, 2019).
atypical lipomatous tumor (10 papers, 2010 to 2025). An intermediate, locally aggressive lipomatous neoplasm. "Well-differentiated liposarcoma (WDL) or atypical lipomatous tumor (ALT) can mimic ASPLT but are characterized by MDM2 and CDK4 positivity, markers that are absent in ASPLT." (PMID 41527615, 2025).
liver fibrosis (10 papers, 2014 to 2025). "MDM2 also interacts with the TGF‐β1 signaling pathway, contributing to liver fibrosis and tumorigenesis." (PMID 40060195, 2025). "Total of 192 potential targets were obtained from 108 active ingredients after removing the redundancy, including MDM2, TNFBR1, MAPK14, and SRC, involved in inflammation, hepatic lipid metabolism, and the development of hepatic fibrosis." (PMID 31354851, 2019). "Furthermore, MDM2 undergoes NEDDylation, increasing HBx stability and accelerating HBV‐induced liver fibrosis." (PMID 40060195, 2025).
myxoid liposarcoma (10 papers, 2013 to 2025). A liposarcoma characterized by the presence of round non-lipogenic primitive mesenchymal cells and small signet ring lipoblasts within a myxoid stoma with a branching vascular pattern. "Of the selected target genes, AMACR and TRIO in 5p and CDK4, HMGA2 and MDM2 in 12q showed significantly (p < 0.05) elevated expression in relation to myxoid liposarcomas." (PMID 28652867, 2017). "At RNA sequencing, significantly elevated expression, compared to myxoid liposarcomas, was seen for TRIO and AMACR in 5p and of CDK4, HMGA2 and MDM2 in 12q." (PMID 28652867, 2017). "The amplification of MDM2 gene identified by FISH in this case was not a specific genetic change of myxoid liposarcoma." (PMID 36123846, 2022). "Fluorescence in situ hybridization (FISH) analysis was done in some of the studies before, which revealed FUS/EWSR1-DDIT3 fusion to be negative and also the absence of MDM2 amplification in this type, which differentiates MPLPS from the conventional myxoid liposarcoma." (PMID 39192930, 2024).
B-cell lymphomas (9 papers, 2011 to 2024). "Although MYC was suggested to drive MDM2 expression based on its association with the MDM2 promoter in B cell lymphoma cells, to our knowledge, this is the first demonstration that MYC overexpression upregulates MDM2 protein." (PMID 33425720, 2020). "Intriguingly, the Mdm2 C305F mutation was recently shown to significantly accelerate B cell lymphomagenesis in an Eμ-Myc induced mouse model of B cell lymphoma." (PMID 21747916, 2011). "Additionally, the Mdm2 C305F mutation was recently shown to significantly accelerate B cell lymphomagenesis in an Eμ-Myc induced mouse model of B cell lymphoma." (PMID 21747916, 2011).
Burkitt lymphoma (9 papers, 2015 to 2025). A rare form of malignant mature B-cell non-Hodgkin lymphoma. "MDM2 overexpression in Burkitt's lymphoma is mainly associated with post-transcriptional modifications and is not caused by MDM2 gene." (PMID 39263534, 2024). "In contrast to the other samples, the harboring patient was HIV+ with serologic evidence of an EBV-infection, a known cause of Burkitt-lymphomas, which frequently harbor mutations in the ARF/MDM2-gene." (PMID 30823914, 2019).
oral squamous cell carcinoma (9 papers, 2008 to 2023). "The aim of this study was to evaluate E2F2, MDM2 and p16 concentrations in the tumour and margin samples of oral squamous cell carcinoma and to assess their association with some selected sociodemographic and clinicopathological characteristics of the patients." (PMID 37185737, 2023).